ATM (ATM serine/threonine kinase)
Diseases named in the same sentence as ATM in open-access papers (continued):
Sharing a sentence is not in itself a finding about the gene and the disease.
cancer (continued). "It is encoded by the ATM gene, in which homozygous loss-of-function germline mutations cause the inherited syndrome Ataxia-Telangiectasia, which is characterised by sensitivity to radiation and elevated cancer risk." (PMID 40723241, 2025). "ATM was associated with the most cancer pairs with a posterior probability > 0.8 (9 pairs)." (PMID 40073867, 2025). "Valuable data to include MM in the spectrum of cancers associated with ATM mutations were also obtained when tissue samples from fourteen MM patients with germline heterozygous ATM variants classified as pathogenic or variants of uncertain significance were investigated." (PMID 41331641, 2025). "For example, cancer cells harboring BRCA1/2 or ATM mutations exhibit a lasting response to ICIs." (PMID 40332379, 2025). "Other homologous recombination DNA damage repair (HR-DDR) genes associated with other cancer risks besides breast and ovarian, such as ATM (n = 9), BARD1 (n = 4), BRIP1 (n = 2), CHEK2 (n = 5), PALB2 (n = 5), RAD51C (n = 1), and RAD51D (n = 7), accounted for an additional 4% (33/769)." (PMID 40065011, 2025). "Mutations in ATM are mainly associated with ataxia-telangiectasia, an autosomal recessive condition characterised by neurodegeneration, immune deficiency and a predisposition to cancer, particularly haematological cancer." (PMID 41049353, 2025). "Identifying this relation may offer further support for consideration to genetic testing to identify ATM gene carriers based on cutaneous findings given its association with familial cancer predisposition." (PMID 40995169, 2025). "Interestingly, SWCNTs and MWCNTs also had shape effects on promoter methylation of ATM (ataxia-telangiectasia mutated (ATM) protein), and ATM genes normally help prevent cancers." (PMID 40281701, 2025). "People with mutations in the ATM gene may also have an increased sensitivity to radiotherapy and certain chemotherapeutic agents used in cancer treatment." (PMID 39996890, 2025). "Mutations in HR genes can cause genome instability and predisposition to cancer; for example, ataxia telangiectasia, Nijmegen breakage syndrome, and Bloom syndrome are caused by mutations in ATM, NBN, and BLM, respectively, and are associated with pleiotropic cancer susceptibility." (PMID 39870965, 2025). "Targeting ATM in tumours rich in myofibroblastic cancer-associated fibroblasts enhance CD8+ T-cell infiltration and improves responsiveness to immunotherapeutic interventions, providing a compelling rationale for combining ATM inhibitors with immune checkpoint blockade therapies." (PMID 40256842, 2025). "Studying mutations and variants of uncertain significance in ATM could improve understanding of how mutations in these genes contribute to cancer and whether ATM should be considered as BRCA3." (PMID 40259910, 2025). "Early studies demonstrated that depletion of ATM induces PARPi sensitivity, indicating that ATM-mutated cancers might benefit from PARPi therapy." (PMID 39994444, 2025). "ATM is a moderate-penetrance cancer susceptibility gene and is one of the HR DNA regulators." (PMID 39984762, 2025). "Similarly, loss of ATM function (common in many cancers) forces a compensatory reliance on the ATR pathway, creating another potent synthetic lethal context." (PMID 41409249, 2025). "ATM, known for its DNA double‐strand break repair role, is often mutated in various human cancers." (PMID 39866838, 2025). "This metabolic reprogramming suggests that combinatorial strategies involving ATM inhibitors and driver oncogene inhibitors could enhance therapeutic efficacy in cancers driven by oncogenic mutations." (PMID 40256842, 2025). "These uncertainties have been highlighted at the first international workshop of the ATM and cancer risk group, stating that ATM pathogenic variant carriers may benefit from tailored, effective cancer risk assessment and management." (PMID 39984762, 2025). "Here we show that loss of SETD1A also confers PARPi resistance in ATM-deficient cancer cells." (PMID 39994444, 2025).
cancer (continued). "Preclinical studies confirm that inhibitors of poly-ADP-ribose polymerases (PARP-1, PARP-2, and PARP-3) may also be helpful in the treatment of CRC and other cancers associated with less common gene mutations such as ATM, CHECK2, PALB2, and RAD51." (PMID 39771554, 2024). "In BM32, cancer cells with serine/threonine kinase (ATM) mutation could be specifically targeted by trametinib (MEK inhibitor)." (PMID 38985431, 2024). "PVs in BRCA1, BRCA2, CHEK2, and ATM have been linked to a wide variety of cancers." (PMID 38929805, 2024). "A potential additional rule of the identified ATM variant in cancer predisposition of this patient might also be considered." (PMID 39684891, 2024). "Additionally, the ATM variant c.8560C>T (p.Arg2854Cys), located in the kinase domain, showed deleterious in silico predictions and increased frequency in cancer cohorts, compared to controls." (PMID 39590369, 2024). "And ATM mutation was highly correlated with lymph node metastasis in cancer tissues." (PMID 38886866, 2024). "Our results highlight that the PARPi synthetic lethality phenotype observed in ATM-deficient cancer cells may be regulated through the subsequent loss of BRCA1/2." (PMID 38807759, 2024). "This treatment regimen was tailored based on comprehensive genomic profiling, which identified mutations in the POLE (catalytic subunit of DNA polymerase epsilon) and ATM (ataxia-telangiectasia mutated) genes, both of which have been implicated in the pathogenesis of various malignant tumors." (PMID 38933440, 2024). "ATM is mutated in ~5% of all cancers, but up to 10% of digestive adenocarcinoma." (PMID 38909137, 2024). "Combining ATR and PARP inhibitors potentiates the cell death of ATM-deficient cancer cells, which may benefit immunotherapy treatment." (PMID 38630271, 2024). "Given the demonstrated increased risk for autosomal dominant and recessive disease, individuals with likely pathogenic/pathogenic (LP/P) variants in ATM may elect to increase cancer surveillance and/or be counseled for family planning." (PMID 38854136, 2024). "Epidemiological studies show that obligate heterozygote parents of individuals with AT reveal an increased risk of cancer, which may be true of ATM heterozygotes in the general population." (PMID 38338943, 2024). "Preclinical studies suggest that cancer cells with alterations in other homologous recombination (HR) repair pathway genes (e.g., ataxia telangiectasia mutated (ATM) and partner and localizer of BRCA2 (PALB2) may also be sensitive to PARP inhibition." (PMID 39085400, 2024). "One can investigate the ordered events in the DNA damage sensing and response in different cellular backgrounds including repair-deficient cells such as BRCA mutation or other cancer susceptibility states (ATM, mismatch repair, Fanconi, PTEN, Wnt/beta-catenin/APC, Rb, etc.)." (PMID 38709242, 2024). "It showed single-agent activity, as well as synergistic activity in combination with cisplatin, especially in advanced cancers with ATM aberrations confirming synthetically lethal interaction between ATM deficiency and ATR inhibition during the phase 1 clinical studies." (PMID 38279263, 2024). "Indeed, many studies reported that the expression of genes involved in the DDR, including ATM, are frequently attenuated during tumor progression, and mutations in these genes confer increased susceptibility to cancer occurrence." (PMID 36746533, 2023). "Consideration should be given to a broadening of the ATM-cancer susceptibility syndrome phenotype within hereditary cancer testing guidelines, as this has the potential to improve the detection of affected patients and facilitate the use of more effective cancer treatments." (PMID 36865800, 2023). "ATM, therefore, has been linked to cancer since its discovery." (PMID 36650267, 2023).
cancer (continued). "In particular, DSBs are known to be critical damage events that cause cell death, and the inhibition of ATM-initiating DSB repair could generate more lesions in the cancer genome." (PMID 37514113, 2023). "The heterogeneity in cancers documented among our patients with germline ATM variants and their families further emphasizes the value of pan-cancer panels, and certainly the importance of including ATM in multi-gene panels testing for hereditary cancer predisposition." (PMID 36865800, 2023). "Targeting ATR may exploit synthetic lethality in cancer cells with impaired compensatory DDR through ATM loss, whether as monotherapy or combined with DNA-damaging drugs." (PMID 36797243, 2023). "We observed that two of the six patients had a personal history of known ATM-associated cancers." (PMID 36865800, 2023). "Similarly, the improved outcome associated with ATM mutation across cancer types is pronounced when only considering women (HR = 0.33, P = 0.01) and is reduced when the analysis is restricted to men (HR = 0.68, P = 0.07)." (PMID 37390209, 2023). "Pre-clinical research indicates that loss of ATM could sensitize cancer cells for DNA-PK inhibition." (PMID 37120674, 2023). "Preclinical models have shown that TNBC, BRCA mutant and ATM-deficient cancer may be highly sensitive to the combination of PARP inhibitors and DNA damage response kinase inhibitors such as ATR inhibitors." (PMID 37773077, 2023). "Therefore, ATM plays a critical role in maintaining genomic stability and reducing the risk of cancer and other diseases." (PMID 36156462, 2023). "Our data indicate that an ATM inhibitor combination might be a better therapeutic paradigm in APE1 deficient cancer cells under the oxidative damage stress, largely due to the already defective NHEJ activity." (PMID 36894994, 2023). "Homozygous ATM mutation underlies a human genetic disorder characterized by immune dysfunction, reproductive, mobility and neurological defects and, importantly, predisposition to cancer." (PMID 37190230, 2023). "They suggested that the co-administration of PARP and ATR inhibitors may be useful for the treatment of cancer types that show deficiency in ATM." (PMID 36975494, 2023). "In our series, neither Patient 4 nor Patient 6 met guidelines for hereditary cancer testing based on their personal or family history of cancer, illustrating circumstances in which ATM germline variants may go undetected." (PMID 36865800, 2023). "Additionally, ATM P/LPVs are also associated with a slight increased risk of OC, pancreatic and prostate cancer." (PMID 36980956, 2023). "Furthermore, increased numbers of cytotoxic CD8+ T cells and activated DCs in TIME are observed in cancers with ATM gene mutations." (PMID 37174688, 2023). "In this study, we demonstrated that the combined treatment with ataxia telangiectasia-mutated serine/threonine kinase (ATM) inhibitor (ATMi) and Chk1 inhibitor (Chk1i) exerts synergistic antitumor effects and induces cancer-specific synthetic lethality at low doses." (PMID 36765693, 2023). "Patients with A-T, ATLD1, and NBS show a predisposition to cancers, including breast cancer, bladder cancer, melanoma, lung cancer, colon cancer, leukemia, and lymphoma, thereby implying the tumorigenic effects of mutations in ATM, MRE11A, and NBS1 genes." (PMID 37098078, 2023).
cancer (continued). "Larger sample sizes will be needed to systematically investigate whether specific germline ATM variants confer a greater risk for atypical ATM cancers." (PMID 36865800, 2023). "To better understand the influence of germline and somatic ATM variants on carcinogenesis in these atypical ATM cancers, we pooled the cancer sequencing data to examine the relationship between ATM alterations and the alteration of other genes in the DNA damage response and cell cycle pathways." (PMID 36865800, 2023). "Our study might provide valuable insights related to the treatment of high-risk NB patients showing ATM zygosity and aggressive cancer progression." (PMID 37020276, 2023). "In particular, low ATM expression, which might exhibit a phenotype similar to that of ATM inhibition, was associated with better OS in cancer patients treated with ICB." (PMID 37174688, 2023). "Given the interplay between DNA repair pathways, the loss of function of ATM in cancer cells could create an enhanced reliance on the remaining ATR or DNA-PK dependent pathways to repair DNA damage." (PMID 37627223, 2023). "Somatic mutations or deletions of ATM are commonly found in a variety of cancers." (PMID 36778120, 2023). "More broadly, these pathway interactions illustrate how germline ATM pathogenic variants may influence the acquisition of somatic alterations throughout cancer initiation and progression." (PMID 36865800, 2023). "Notably, the study illuminates that Stromal antigen 2 (STAG2) deficient cancer cells manifest heightened sensitivity to ATM inhibition." (PMID 37985839, 2023). "Interestingly, one case carrying the truncating variant R805X in ATM has suffered for five different cancers and shows a severe cancer familiarity." (PMID 35347810, 2022). "Furthermore, the authors showed that regularly substituted ATM deficient mice developed cancer significantly later, suggesting that oxidative stress plays a role in lymphomagenesis in these animals." (PMID 35454905, 2022). "Our model is supported by several recently reported cancer-associated MR DNA DSB separation-of-function mutants that maintain Mre11 nuclease function while losing the ability to signal the presence of the DNA DSB through ATM or vice versa." (PMID 35084331, 2022). "Combinations with BRAF inhibitors in BRAF mutated cancers with ATM mutations or other homologous recombination defects could be a prime target." (PMID 36079062, 2022). "Therefore, cancer risks associated with ATM variants are of relevance to genetic counselling and cancer risk management of a much larger population." (PMID 36555667, 2022). "The ATM variant (rs28904921) was recently compared to other pathogenic missense or truncating variants in the ATM gene in a large cohort of 627,742 hereditary cancer patients and found a higher increased risk of invasive ductal BCa (OR 3.76, 95% CI 2.76–5.21) for carriers of this variant." (PMID 36315513, 2022). "A review of the molecular and cellular features of the major cancer syndromes associated with radiosensitivity revealed the importance of the ATM protein, either as an impaired kinase in the nucleus or as a complex in the cytoplasm, with the mutated protein responsible for the syndrome." (PMID 36551628, 2022). "Cancer screening was performed in two patient with the FH and ATM mutation." (PMID 35719373, 2022). "Loss of ATM disturbs balance between the glutathione reduced form and oxidized form by ROS or oxidized thiols, leading to oxidant homeostasis impairment, which contributes to the A-T phenotype, especially cancers." (PMID 35203601, 2022). "Mutations in tumor suppressors FBXW7 and ATM display a higher prevalence in BRAF mutated cancers." (PMID 36079062, 2022).
cancer (continued). "In vivo data argue that a targeted inhibition of the 9-1-1 complex such as with HUS1 may be an effective strategy for the treatment of ATM-deficient and other cancers." (PMID 35456300, 2022). "Since ATM plays a pleiotropic role in the maintenance of the genome, elevated cancer risk may be caused by haploinsufficiency or the second hit, i.e., the loss of the active allele." (PMID 35457081, 2022). "The association of ATM gene mutation/deletion with STS suggested a link of the ATM gene with cancer risk, and ATM kinase may contribute to the pathogenesis of STS." (PMID 36430780, 2022). "Initially, the ataxia–telangiectasia mutated (ATM) gene was identified via the observation of ataxia–telangiectasia (A–T) patients, who present with gait disorder (ataxia), dilated capillaries (telangiectasia), and high sensitivity to cancer radiotherapy." (PMID 36253861, 2022). "The ATM gene is a DNA-damage response gene that is commonly mutated in cancer." (PMID 35402245, 2022). "Furthermore, even radiotherapy, independently of immunotherapy, is able to reduce xCT expression in cancer cells through the activation of an ataxia-telangiectasia mutated (ATM)-dependent transcriptional program." (PMID 36338517, 2022). "This approach is validated by the observation that known SMYD3 interactors, such as VGFR1, which is involved in cancer hallmark “inducing angiogenesis”, and ATM and BRCA2, which are involved in cancer hallmark “genome instability & mutation”, show a significant enrichment in P-tripeptides." (PMID 35495117, 2022). "Mutations in ATM are responsible for Ataxia-telangiectasia (AT), which is a rare, autosomal recessive disorder characterized by cerebellar degeneration, immunodeficiency, sensitivity to radiation, and cancer susceptibility." (PMID 35076389, 2022). "Interestingly, ATM, a moderate-penetrance cancer susceptible gene, and APC genes were previously reported as key components showing potential for targeted therapy." (PMID 36672847, 2022). "ATM deficiencies may result in increased susceptibility to DNA damage and a predisposition to cancer." (PMID 35807169, 2022). "It has been reported that the loss of ATM expression in AT cells triggers a senescent-like phenotype, including upregulation of genes associated to senescence and cancer, decreased cellular replication capacity, shortening telomeres, and autophagy abnormalities." (PMID 35257272, 2022). "ATR inhibitors are in clinical trials for the treatment of cancers, with patient selection hypotheses including ATM deficiency and high replication stress." (PMID 34329458, 2021). "Moreover, the whole-genome sequencing of cancer patients with somatic or germline mutations has highlighted a high percentage of ATM mutations in the phosphoinositide 3-kinase domain, mostly in cancer cells resistant to classical therapy." (PMID 34771661, 2021). "The second and third most frequent mutations found in different cancer cell lines are ATM and ATR." (PMID 34887439, 2021). "The presence of this additional variant in ATM gene, therefore, may explain, at least partially, the strong family history of cancer." (PMID 34855882, 2021). "Several studies have shown that combinations of RAD51 and ATM variants may increase the risk for cancer development." (PMID 33778923, 2021).